CCL11 (C-C motif chemokine ligand 11)
Diseases named in the same sentence as CCL11 in open-access papers (continued):
Sharing a sentence is not in itself a finding about the gene and the disease.
tumor (continued). "More importantly, Fe-bLf Dox was capable of inducing greater expression of anti-tumour and macrophage homing chemokines such as GM-CSF (1.7 fold), CCL11 (1.8 fold), IL-1ra (1.3 fold), IL-23 (1.5 fold), CCL12 (1.8 fold), CCL4 (1.5 fold) and CCL17 (1.7 fold), than Dox injections." (PMID 27576789, 2016). "Given the observed increase in dentate gyrus white matter reactive microglia and in CCL11 and other CSF cytokines/chemokines, together with spatial memory deficits, we hypothesized that neurogenesis may be impaired following tumor-clearing CAR T cell administration." (PMID 38798554, 2024). "In addition, expression of CCR3, the receptor for CCL11, was also increased in the tumor." (PMID 27119233, 2016). "Here, we identified surgery-induced C-C motif chemokine ligand 11 (CCL11) as a pivotal driver of HCC recurrence through dual mechanisms of immunosuppression and tumor invasiveness." (PMID 41714328, 2026). "Nevertheless, the precise mechanisms and individual contributions of CCL11 in HCC remain poorly understood, compounded by the dualistic nature of eosinophil and other immune cell functions within tumor microenvironments." (PMID 40429807, 2025). "The attraction of MCs to a tumor requires the action of different chemokines produced by the tumor cells such as the stem cell factor (SCF), CXCL2, CCL2, CCL5, CCL11, CXCL12, CCL15, IL-3, and IL-33." (PMID 41465542, 2025). "They directly mediate tumor cytotoxicity when cocultured with MH134 cells (an HCC cell line) in the presence of several mediators, such as IL-5 and CCL11." (PMID 40721870, 2025). "Among them, the high expression of CCL4/CCL11/CCL28 is closely related to the prolonged survival period of patients, suggesting its potential for tumor suppression." (PMID 41445742, 2025). "As verified by exocytotic chemokines, the expression of tumor-promoting chemokines, including CCL3, CCL5, CCL7, CCL11, CXCL1, and CXCL12, showed a downward trend after MWA." (PMID 38779358, 2024). "CCL11, also known as eotaxin, a member of the CC chemokine subfamily, recruits eosinophils to the TME, playing an anti-tumor role." (PMID 38305920, 2024). "In comparison to control tumors, those overexpressing miR-29 exhibited the following changes: (i) Elevated levels of anti-tumor cytokines such as CCL5 and CCL11, the transmembrane protein CD40, and the angiogenesis inhibitor endostatin." (PMID 38890285, 2024). "At the same time, extracellular tumor-promoting chemokines, such as CCL3, CCL5, CCL7, CCL11, CXCL1, and CXCL12, were also downregulated." (PMID 38779358, 2024). "Together, these results indicate that ATX negatively regulates AP-1-mediated expression of CCL11 in PDAC cells, suppressing the recruitment of eosinophils into the tumor microenvironment." (PMID 38195933, 2024). "CCL11 was identified as the most potent chemokine in improving immunogenicity, promoting specific CD8 + T-cell stemness and generating tumor rejection." (PMID 38459592, 2024). "We conducted IHC staining of CCL11, CD4, and Foxp3 proteins in serial sections of the same tumor tissues from BRCA patients." (PMID 38305920, 2024). "With further growth of the tumor, the immune response gradually changed from anti-tumor to pro-tumor mode, and the high concentration of CCL26 and CCL11 in the TME recruits Th2 cells to the tumor area." (PMID 37063892, 2023). "It induces CCL11 expression, which results in TATE at tumor sites, and increases eosinophil anti-tumor function." (PMID 37587450, 2023). "CCL11 and CCL24 are expressed at lower levels in glandular cells than in stromal cells in CRC tissues, which promotes tumor development." (PMID 37014331, 2023). "During tumor progression, Th2 cells are recruited to the TME by CCR3 ligands (CCL26, CCL11, and so on), and produce IL-4 and IL-10, which induce M2 polarization of macrophages." (PMID 37063892, 2023).
tumor (continued). "Further investigation showed that IL-33 is not only an inducer of CCL11 production and a protector against DPP4, but it also increases eosinophil-mediated tumor cytotoxicity." (PMID 37587450, 2023). "CCL5, CCL-11, CXCL9, and CXCL10 are postulated as the main drivers in eosinophil-mediated tumor cell necrosis." (PMID 36427017, 2023). "The levels of six cytokines differed among groups, including significant elevations in aged DIO mice, relative to the other groups, in the tumor-promoting chemokines CXCL13, CCL7, and CCL11." (PMID 36686775, 2022). "Confocal microscopy analysis showed the cellular co-localization of CCL11 and CCR3 in HNC tumor cells." (PMID 35804913, 2022). "Of the cytokines analysed, nine (CD30L, CCL11, CCL24, IGFBP5, IL-4, IL-13, MIP-3ß, CXCL4 and TPO) were significantly more abundant in 4T1 primary tumours than in 67NR primary tumours (Fig. 4aiii)." (PMID 33795809, 2021). "CCR5 binds many ligands which are overexpressed in the tumor microenvironment including CXCL13 (BCA-1), CCL3 (MIP1α), CCL3L1, CCL4 (MP-1β), CCL8 (MCP2), CCL11 (eotaxin), CCL13 (MCP-4), and CCL16 (HCC-4)." (PMID 33485378, 2021). "Almost all tested parameters (CCL11, CCL24, and CCR3) showed higher SE than commonly used tumor marker CA 19-9." (PMID 34204490, 2021). "We found that cabozantinib treatment significantly upregulated CCL11, CCL12, CXCL12, CCL8 and CX3CL1 in the tumor microenvironment." (PMID 33954115, 2021). "Mechanistically, we found that cabozantinib treatment induced expression of neutrophil-related chemokines (CCL11 and CXCL12) and T cell-related chemokines (CCL8 and CX3CL1) in the tumor microenvironment." (PMID 33954115, 2021). "The extent of tumor metastases was significantly higher in lungs of OVA-exposed mice and increased levels of CCL11 expression were measured after OVA exposure." (PMID 33608009, 2021). "In response to several stimuli such as IL-5, IL-33, CCL11, IFNγ and TNFα, eosinophils secrete cytotoxic proteins (MBP, ECP, EDN and granzymes), which can induce apoptosis of tumor cells." (PMID 33233582, 2020). "IL-4 is generated by both tumor cells and stromal cells, and IL-4 neutralization resulted in reduced levels of the chemokines CCL2, CCL11, and CXCL5 in the TME." (PMID 33178603, 2020). "We also probed for myeloid cells expressing CXCR3 (the receptor for CXCL9-11) and CCR2 (one of the receptors for CCL11 and uniquely a receptor for MCP1) within our tumor digests." (PMID 31940491, 2020). "A hypoxic state of the tumor also induces the upregulation of C-C motif chemokine 11 (CCL11) and chemokine (C-C motif) ligand 28 (CCL28) capable to recruit Tregs into the tumor microenvironment." (PMID 31370258, 2019). "The expression of both CCL11 and CCR3 on the tumor cells can lead to homotypic aggregation, which can be observed as cohesive clusters of tumor cells, a characteristic finding in ALCL." (PMID 29915722, 2018). "CCL11, a CCR3 ligand, is also expressed by PCALCL cells and is detected in the connective tissue cells in the tumor." (PMID 29915722, 2018). "In summary, the chemokine, CCL11, along with its cognate receptor, CCR3, have been identified as major factors influencing GBM tumor development." (PMID 27119233, 2016). "In Hodgkin lymphoma and cutaneous T cell lymphoma, CAFs secrete the chemokines CCL11 and CCL26 that recruit CCR3(+) T lymphocytes into the tumor and produce high levels of IL-4, a signature of a Th2-dominant microenvironment." (PMID 25110692, 2014). "Chemokines such as C-C motif chemokine ligand 5 (CCL5), C-C motif chemokine ligand 11 (CCL11), C-X-C motif chemokine ligand 9 (CXCL9), and C-X-C motif chemokine ligand 10 (CXCL10) are believed to be primary mediators of eosinophil-driven tumor necrosis." (PMID 40761780, 2025). "Furthermore, recombinant human CCL11 has been shown to expand the CD4+CD25+Foxp3+ regulatory T-cell (Treg) population while upregulating both CCR3 and Foxp3 expression in tumor microenvironments." (PMID 40429807, 2025).
tumor (continued). "As CCR3 is the major receptor of CCL11, we sought to determine whether CCR3 + cells were essential for immunogenic improvement and tumor eradication in vivo." (PMID 38459592, 2024). "Ccl11 overexpression increased eosinophil recruitment into the PDAC microenvironment and was sufficient to increase intratumor apoptosis and reduce tumor growth." (PMID 38195933, 2024). "Moreover, in miR-29 overexpressing tumors, there were significant changes in cytokine and chemokine expression, such as upregulation of CCL5, CCL11, CXCL9, CXCL11, and CXCL16, known for their anti-tumor effects." (PMID 38890285, 2024). "CCL11-OVA prevented the formation of any palpable tumors from either cell lines, indicating that a multiple antigenic response was established to preclude the development of an antigenically heterogeneous tumor." (PMID 38459592, 2024). "Such tumor-mediated prolonged survival was reliant on tumor-secreted CCL11 but independent of IL-5 since anti-IL5-treated mice had eosinophils present in their colons." (PMID 37587450, 2023). "Exogenously administered IL-33 increased the expression of alarmins, Th2 chemokines (CCL17 and CCL22), CD8 + T cell chemokines (CXCL10, CX3CL1), eosinophil chemokines (CCL11, CCL13, CCL24), as well as Th2-related cytokines (IL-4, IL-13) and Th1 effector molecules (granzyme B) in the primary tumor." (PMID 37587450, 2023). "Furthermore, many other different molecules produced by tumor cells or by cells of the TME can induce MC chemotaxis, including CCL2, CCL5, CCL11, CCL15, CXCL12, VEGF, FGF2, osteopontin, and lipid mediators." (PMID 37376140, 2023). "The expression of Il4, Il13, Ccl11, Ccl17 and Ccl22 mRNA was increased two- to fourfold, whereas the expression of Tslp mRNA was not changed, in the skin lesions of Ddx5∆KC mice compared with Ddx5fl/fl mice at day 16 post-MC903 administration." (PMID 36271146, 2022). "In SMMC-7721-tumor-bearing mice, Tf-LP-ERN treatment increased the serum concentration of TNF-α (P < 0.01) and decreased the serum concentrations of IL-10 (P < 0.05) and CCL11 (P < 0.05)." (PMID 34513705, 2021). "Migration to the TME can be mediated by eotaxins (eotaxin-1/CCL11, eotaxin-2/CCL24, eotaxin-3/CCL26) that bind the CCR3 receptor highly expressed on eosinophils and by alarmins (i.e., HMGB1 and IL-33) released from dying tumor cells." (PMID 33329534, 2020). "The adverse prognostic impact of CCL11 in SCC- and AEG-tumors could be explained by the different immunogenic profile of the different tumor entities." (PMID 28537901, 2017). "Fusion antigens with CCL11 expanded the TCR diversity of specific T cells and induced the infiltration of activated specific T cells, neutrophils, macrophages and dendritic cells (DCs) into the tumor, which created a comprehensive immune microenvironment lethal to tumor." (PMID 38459592, 2024). "We also tested whether vaccination with antigen fused with CCL11 eliminated tumor cells without antigen expression in a prophylactic model." (PMID 38459592, 2024). "Il11, Il6, Ccl11, Mdk and Ptn have also been shown to play key roles in cancer progression and immune modulation, suggesting that altered expression of these genes in KPC-Cdh11+/- mice may contribute to changes in tumor immune profile." (PMID 37954069, 2023). "Ddx5 was increased in the whole skin lesions of MC903- or IMQ-treated Cd93–/– mice compared with their wild-type counterparts, along with fewer plaques on the ears or dorsal skin and reduced expression of Il4, Il13, Ccl11, Ccl17 and Ccl22 or Cxcl1, Cxcl2, Ccl20, Il23, Il17a and Il36γ." (PMID 36271146, 2022).
tumor (continued). "We found that circulating levels of CCL11, GCSF, GMCSF, MCSF, TNFα, and IL12 (p70) were higher in TKTB34-RAS tumor-bearing mice compared with control group without tumors." (PMID 38651826, 2024). "However, other CCLs, including CCL2, CCL3, CCL11, CCL26, and CCL28, did not exhibit significant changes in expression during tumor progression." (PMID 39859340, 2025). "DPP4 enzymatic activity has been shown to reduce both T‐cell and eosinophil migration to sites of tumor by inactivating the T‐cell chemokine CXCL10[8b] and the eosinophil chemokine CCL11.[8c] Here, we extended these findings by showing the nonenzymatic activity of DPP4 in cell migration." (PMID 36683148, 2023).
infection (89 papers, 2009 to 2026). The state of being infected such as from the introduction of a foreign agent such as serum, vaccine, antigenic substance or organism. "While isolates induced several common immune host responses to infection, one B.1 isolate was unique in the promotion of eosinophil-associated proteins IL-5 and CCL11." (PMID 36992320, 2023). "The infection also induced IL-1α production, but inhibited CCL11 and IL-17 in both WT and deficient mice." (PMID 35479068, 2022). "In mice, pro-inflammatory CSF cytokines/chemokines were elevated for at least 7-weeks post-infection; among the chemokines demonstrating persistent elevation is CCL11, which is associated with impairments in neurogenesis and cognitive function." (PMID 35043113, 2022). "In support of this, via transcript analysis of peritoneal cells we identified a significant reduction in CCL11 (eotaxin 1) expression in IL-4Rα deficient mice 6 days after infection with BmL3." (PMID 29547639, 2018). "Overall infection with the L6 lineage was associated with greater increases of cytokines with anti-inflammatory (IL-1RA and IL-13) or Th2-like activity (IL-13 and CCL11)." (PMID 29813061, 2018). "As expected, we found that CCL11 together with CCL2, CCL3, and the receptors CCR2, CCR3, and CCR5 were all upregulated in newly-weaned hamster brain tissues after Delta variant infection at 2, 4, and 7 dpi, of which CCL11 and CCR2 were significantly higher at 4 dpi." (PMID 37122119, 2023). "Using cytokine arrays and spatial transcriptomics we show that STm infection triggers the release of the eosinophil chemoattractant CCL11 by specific macrophage populations in MLN during the chronic phase of infection." (PMID 39801515, 2025). "We confirmed that the MLN levels of CCL11 were significantly higher 1–4 w.p.i compared to the levels prior to infection." (PMID 39801515, 2025). "In both the B.1.351 model and the AAV-hACE2-WA1 model, intranasal SARS-CoV-2 infection resulted in increases in pro-inflammatory cytokines (e.g., IL-1β, IFNβ, CXCL10, IFNγ, IL-6, and CCL11) in the hippocampus and cerebrospinal fluid at 7 days post-infection." (PMID 39861887, 2025). "Combining spatial transcriptomics and experimental manipulations, we found that macrophages responding to STm infection recruited eosinophils in a C-C motif chemokine ligand 11 (CCL11)-dependent manner and enhanced their activation." (PMID 39801515, 2025). "CCL11 concentrations were significantly elevated in the breakthrough infection mice at 1 DPC compared to the primary infection mice, but otherwise were at similar concentrations as all other treatment groups at the remainder of the time points." (PMID 41190814, 2025). "Once the infection is established, eosinophils accumulate near parasites or sites of tissue damage, with CCL11 (eotaxin-1) and its receptor CCR3 being important in this process." (PMID 37947530, 2023). "Clca1, Muc5ac, and Ccl11 were confirmed to be highly up-regulated during infection in WT mice but impaired in Il13−/− mice." (PMID 34127548, 2021). "After early neutrophil (2 h.p.i.)and monocyte (6 h.p.i.)chemoattractants secretion, eosinophil chemoattractants—CCL5 (RANTES) and CCL11 (eotaxin)—secretion follows while the hRSV infection continues, the latter occurring around 12 h.p.i.." (PMID 32545470, 2020). "Accordingly, we found increased RNA abundance of Arg1, Socs1, Sra1, Saa1, Ciita, Marco, Mgl2, Cd209d, Cd209e, Cd209f, Ccl1, Ccl11, Ccl17, Ccl19, Ccl20, Ccl22, and Ccl24 genes in Stat2−/− mice when compared to WT mice during super-infection." (PMID 30337919, 2018). "Especially the chemokines CCL3, CCL5, and CCL11 increased in the lower infection groups 3 months after treatment." (PMID 30619332, 2018). "Our former research showed CCL8 and CCL11 in mouse brain samples increased gradually in parallel with the rising eosinophil counts in blood after infection." (PMID 26070790, 2015).